TERT (telomerase reverse transcriptase)
Diseases named in the same sentence as TERT in open-access papers (continued):
Sharing a sentence is not in itself a finding about the gene and the disease.
cancer (continued). "Although cancers with TERT promoter mutations occur across a seemingly disparate subset of cancer types, they are now known to be common in those that display RAS pathway expression profiles and mesenchymal traits." (PMID 40560846, 2025). "Telomerase reverse transcriptase (TERT) is a ribonucleoprotein polymerase maintaining telomere length and abnormal telomerase activation is known to cause immortalization of cancer cells." (PMID 40437181, 2025). "Unlike the infrequent occurrence of mutations in the coding region of the TERT gene, mutations in the TERTp are notably frequent in some human cancers." (PMID 39596624, 2024). "Telomerase is enriched in tissue stem cells and activated in many cancers by somatic TERT promoter mutations." (PMID 39020172, 2024). "Increasing evidence has shown that TERT gene variants are associated with the risk of developing, surviving, and prognosing various cancers." (PMID 38197421, 2024). "TERT (telomerase reverse transcriptase) gene mutations, particularly in the TERT promoter, are widely recognized as molecular markers that are closely linked to high aggressiveness and poor prognosis in many malignant tumors." (PMID 39457636, 2024). "While previous studies in the context of multiple cancer types identified functional variants regulating TERT expression, due to its inactivation in normal differentiated tissues, eQTL of TERT has not been detected in the GTEx lung tissues." (PMID 39266564, 2024). "TERT (Telomerase Reverse Transcriptase) promoter mutations are genetic alterations that can be found in many different cancers, including some CNS tumors." (PMID 39375809, 2024). "In humans, two hotspot TERT promoter mutations, C228T and C250T (Hg19), are associated with several cancers." (PMID 38232086, 2024). "TERT promoter mutation and methylation are strongly associated with increased telomerase activation in cancer cells." (PMID 38275760, 2024). "Herein, we uncovered that the PLK1 inhibitors prefers to inhibit the growth of HCC cancer cells harbouring TERT promoter mutations." (PMID 38769666, 2024). "Through a variety of processes, including amplification of the hTR-encoding genes TERC and TERT, telomerase activity increases in cancer." (PMID 39239547, 2024). "TERT promoter mutations are found to be more prevalent among male patients than their female counterparts with most cancer types, except for HNC where the opposite held true." (PMID 37462445, 2024). "Although there are two hot spot TERT promoter mutations (G228A at −124 bp and G250A at −146 bp upstream the translation start site) in human cancers, G228A occurs dominantly in HCC." (PMID 38769666, 2024). "TERT encodes telomerase reverse transcriptase, the catalytic subunit of the enzyme telomerase, which plays a critical role in most human cancers by ensuring telomere length and subsequent chromosomal stability and preventing cellular senescence." (PMID 39456495, 2024). "Overall, our results add to the growing body of the literature that serves to enhance our understanding of the variation in TERT promoter mutations across cancer types, sex, and race." (PMID 37462445, 2024). "The frequency of TERT gene mutations was significantly higher in cancer tissues than benign nodules (27/124, 21.77% vs. 2/58, 3.45%, p = 0.094), thus suggesting the value of this gene in distinguishing benign from malignant thyroid nodules." (PMID 38886866, 2024). "We showed that reduced or elevated cancer risk associated with a multi-cancer GWAS locus at chr5p15.33 marked by the SNPs rs2242652 and rs10069690 is related to the genetic regulation of TERT splicing by rs10069690 and VNTR6–1, a 38-bp intronic tandem repeat." (PMID 39802763, 2024). "Non-coding mutations in the TERT promoter (TERTp), typically at one of two bases −124 and −146 bp upstream of the start codon, are among the most prevalent driver mutations in human cancer." (PMID 39557834, 2024).
cancer (continued). "The prevalence of TERT gene promoter mutations varies among patients with cancer based on race and sex." (PMID 37462445, 2024). "Examining the differences in the distribution of TERT promoter mutations by race, it was notable that there were differential distributions among patients with the same cancer type but belonging to different racial groups." (PMID 37462445, 2024). "For example, correcting TERT promoter mutation using base editing can inhibit the cancer phenotype in vivo." (PMID 39544254, 2024). "It is indicated that TERT overexpression, caused by promoter mutation, is attributed to telomerase abnormal activation in cancer, although only a small portion of cancer patients are recognized as having TERT mutation." (PMID 38278800, 2024). "These alterations have been reported in multiple cancer types, especially TERT promoter mutations, which are associated with increased TERT expression." (PMID 38278800, 2024). "There is a high frequency of TERT promoter mutations in various cancer types that predict poor outcomes in patients." (PMID 39228402, 2024). "TERT is not expressed in most human somatic cells; however, its expression and transcription are upregulated in many cancers through various mechanisms, including mutations in the core promoter region of the TERT gene." (PMID 38927493, 2024). "TERT promoter mutations are more frequent in cancers derived from tissue with low potential for self-renewal and mostly occur at an early stage of molecular dedifferentiation." (PMID 38392213, 2024). "Genetic modifications to increase telomerase expression through TERT promoter mutations have been shown to extend lifespan and delay cancer onset in some transgenic mouse models, although they also increase cancer risk in others." (PMID 39126110, 2024). "This patient also harboured a variant in the TERT promoter (TERTp), which, although classified as a polymorphism (MAFgnomAD_NFE of ~30%), is associated with an increased risk of cancer." (PMID 38396644, 2024). "One notable example is the telomerase reverse transcriptase (TERT) promoter, which is a hotspot of mutation in multiple cancer types." (PMID 39544254, 2024). "Mutations of the TERT-promoter alter cellular senescence and represent an early and one of the most common mutations in a vast variety of cancers." (PMID 38392213, 2024). "Our pilot study showed that the TERT+ group had ∼13% of cancers with C228T or C250T mutated TERT promoter." (PMID 38859942, 2024). "TERT promoter mutations (TERTp mutations) have been ubiquitously identified across many human cancers, highlighting their critical role in disease progression." (PMID 39078811, 2024). "This extended analysis identified six somatic eQTL-target gene pairs at an FDR of ≤ 0.05, with the somatic eQTL for TERT showing the most significant association, consistent with the pan-cancer TERT signal found earlier." (PMID 39367275, 2024). "The patients in this study had extremely advanced cancer, and TERT promoter mutations were observed in more than 60% of cases." (PMID 38630010, 2024). "TERT activity has been implicated in promoting stem-like features in cancer and its inhibition by RTI promotes cell differentiation." (PMID 38730705, 2024). "All cell lines expressed high levels of TERT mRNA independently of promoter mutation, cancer driver gene, or pathology." (PMID 38744818, 2024). "TERT reactivation that is present in many cancers is caused by the alteration of the TERT promoter (TERTp)." (PMID 39685621, 2024). "Out of the set of molecular genetic events in patients with PTC, the ATA guidelines (2015) recommend using only the BRAF and TERT mutations as markers of cancer with the least favorable prognosis." (PMID 39000197, 2024).
cancer (continued). "The so-called TERT promoter mutations (TPMs), which subvert the transcriptional silencing of TERT, are the most common noncoding mutations in cancer." (PMID 38371417, 2024). "TERT, an oncogene encoding telomerase associated with maintaining telomeres in rapidly dividing cancer cells, is frequently overexpressed in tumors." (PMID 39406235, 2024). "In this study, we report for the first time, differences in the distribution of TERT promoter mutations by race and sex across different cancer types." (PMID 37462445, 2024). "Second, allele-specific regulation of TERT was proposed to explain its activation in human cancer, and an interplay between TERT promoter mutation, methylation, and histone modification were involved in this process." (PMID 38313800, 2024). "TERT promoter mutations have a significantly high prevalence among cancers with aggressive histologic features, those in advanced stages, and those with distant metastases." (PMID 38630010, 2024). "Although driver mutations tend to occur predominantly in coding regions, a notable exception is that there is a high frequency of activating mutations in the TERT promoter, highlighting the importance of telomerase activation in human cancer." (PMID 39365046, 2024). "TERT gene promoter mutations have been explored as biomarkers of improved survival for patients with cancer receiving immune checkpoint inhibitors." (PMID 37462445, 2024). "At least ten independent pleiotropic multi-cancer GWAS signals within the ~100 kb genomic region on chromosome 5p15.33 harboring TERT and CLPTM1L have been associated with cancer risk or protection." (PMID 39802763, 2024). "Mutations in TERTp lead to increased TERT expression and de novo telomerase activity in a cancer cell." (PMID 36776000, 2023). "The protein encoded by the TERT gene, telomerase reverse transcriptase, contributes to cancer cell survival by maintaining telomere length and avoiding activation of cell senescence." (PMID 36882706, 2023). "About 16% of cancers in the Pan-Cancer Analysis of Whole Genomes (PCAWG) dataset were found to harbor somatic mutations in at least one of these three genes (TERT, ATRX, and DAXX) involved in telomere maintenance." (PMID 37761808, 2023). "Since the discovery of the non-coding driver mutations in the TERT promoter, the field of cancer genomics has shown a great interest in searching for ‘the other TERTs’." (PMID 36625266, 2023). "Accordingly, mutations in the coding region of TERT can affect telomerase activity and telomere length and generate severe clinical phenotypes, including increased cancer frequency." (PMID 36768147, 2023). "Resveratrol also inhibits the expression of TERT in metastatic glioblastom cancer cells, a phenomenon associated with dose-dependent prevention of cell proliferation and tumor regression." (PMID 36237161, 2023). "As an example, small molecules that cause disruption of Myc/Max heterodimerization on TERT promoter and proteasome-mediated degradation of Myc have been shown to suppress cell proliferation in diverse cancer cell lines." (PMID 38033865, 2023). "Perhaps inclusion of variants more directly linked to cancer initiation such as SNPs at the WNT or TERT loci and rare variants in cancer-associated genes will improve genetic risk assessment." (PMID 38163482, 2023). "Genome-wide association studies (GWAS) have demonstrated that single nucleotide variants (SNVs) at chromosome 5p15.33, which contains the TERT gene, are significantly associated with cancer risk." (PMID 36768147, 2023). "In 2008, it was shown that the genes regulated by TERT appear to be similar to the genes regulated by c-Myc and Wnt, two factors associated with cell stemness, differentiation and cancer." (PMID 37189709, 2023).
cancer (continued). "In this study, we set out to identify regulated and dysregulated TERT splice variant expression to identify a potential cancer therapeutic window." (PMID 37531400, 2023). "The recent discovery of TERT promoter mutations has dramatically increased our understanding about the steps that lead to cellular immortality of cancer cells by telomerase reactivation." (PMID 36805596, 2023). "For example, TERT overexpression, a major contributor to cancer, is caused by multiple NCVs in its promoter that create ETS factor binding sites." (PMID 36808133, 2023). "Mutations in the TERT gene increase transcription from the TERT promoter, thereby preventing cancer cells from undergoing apoptosis." (PMID 37762707, 2023). "The TERT promoter region has been described as one of the most frequently mutated non-coding cancer drivers." (PMID 37993930, 2023). "For instance, TERT overexpression in cancer cells enhances autophagy, while TERT‐deficient cells exhibit impaired autophagic flux." (PMID 37501354, 2023). "In the TERT promoter mutation cancer panel, we found four DEGs specific to TERT promoter mutational status: AC103834.1, FP700111.1, AC021321.1, and RN7SL8P." (PMID 37568598, 2023). "Among the several mechanisms of hTERT activation, TERT somatic promoter mutations are the most common non-coding driver mutations in cancer and occurred at a high frequency in over 50 cancer types." (PMID 36979671, 2023). "In the current cancer cohort studies, bpb3 correctly predicted significant TF binding affinity changes at mutation blocks near the promoter of TERT and BCL2 genes in MN and FL, respectively." (PMID 37520692, 2023). "Our data revealed that our methods accurately predicted splicing factors that would impact TERT splice variant expression ratios in cancer cells." (PMID 37531400, 2023). "TERT promoter mutations in various reports of different cancers have been associated with aggressive characteristics, poor outcomes, and shorter survival." (PMID 36979671, 2023). "In particular, BRAF V600E and TERT mutations are frequently reported in a subgroup of cancers with more aggressive clinicopathological behaviors." (PMID 37173884, 2023). "TERT rs2242652 has also been implicated in the susceptibility for developing other cancers but the direction of association seems to vary between cancer types." (PMID 35788059, 2023). "In clinical cancer research, it was found that there was a site mutation in the promoter region of telomerase reverse transcriptase (TERT) gene." (PMID 37519297, 2023). "The TERT gene encodes the catalytic component of telomerase, a ribonucleoprotein that plays a pivotal role in cancer initiation via telomere-dependent or telomere-independent pathways." (PMID 38084250, 2023). "Lastly, we identified splicing factors that are predicted to impact TERT splice variant expression only in cancer cells, only in stem cells, or in both cell types." (PMID 37531400, 2023). "Out of all samples, 25 showed TERTp mutations, with the majority of the variants preferentially accessible in cancer cells, which was also in accordance with high TERT expression from snRNA-seq data." (PMID 37914932, 2023). "In this study, we focused on investigating polymorphisms within the CLPTM1L VNTR region, which belong to a cancer-associated region containing the TERT gene located at the p-arm end of chromosome 5." (PMID 38254939, 2023). "To investigate the potential of ASEE in cancer, we here explored this approach by targeting variants at the TERT promoter region." (PMID 37993930, 2023). "Associations between TERT rs2242652:A and the 10 most frequent cancers were explored in the UKB and FinnGen (FG) cohorts." (PMID 35788059, 2023).
cancer (continued). "In this review, we summarize recent findings on the role of TERT promoter mutations, telomerase expression and telomeres elongation in cancer development, their clinical significance and therapeutic opportunities." (PMID 38033865, 2023). "The Pan-Cancer Analysis of Whole Genomes consortium, investigating 2,658 tumors from 38 cancer diagnoses, highlighted the prevalence of TERT promoter mutations but reported a very limited number of new potential driver events in noncoding regions." (PMID 37549291, 2023). "TERT suppression causes apoptosis or increases the sensitivity of cancer cells to apoptotic stimuli ex vivo and in vivo, regardless of the telomeric function." (PMID 37189709, 2023). "Next, we aimed to determine if cell density impacted cancer cell TERT splice variant expression similar to iPSCs." (PMID 37531400, 2023). "Only cancer cell lines presenting TERT promoter mutations exhibited the H3K4me2/3 active chromatin marks and recruitment of the GABPA/B1 transcription factor to the cognate binding sites." (PMID 38033865, 2023). "Another interesting study also revealed the cooperative function of p52 with transcription factor ETS1 in the reactivation of telomerase in cancers via a hotspot −146 C > T TERT promoter mutation." (PMID 36899924, 2023). "We next set out to evaluate ASEE in a different cancer cell line now addressing the THOR region of the TERT promoter using a frequent common SNP for allele discrimination." (PMID 37993930, 2023). "Surprisingly, the minor allele frequency (MAF) among cancer-free controls for the TERT (rs2736098*A allele) was 0.33, while the minor allele frequency for the TERT (rs2736100*T allele) was 0.46." (PMID 37884663, 2023). "We also investigated the accessibility of TERT promoter (TERTp) with hotspot mutations in cancer and normal cells." (PMID 37914932, 2023). "Recent studies have demonstrated that TRF2 binds the TERT promoter G-quadruplex and recruits the polycomb-repressor EZH2/PRC2 complex causing H3K27 trimethylation and TERT promoter repression both in cancer and normal cells." (PMID 38033865, 2023). "We utilized a novel model to investigate TERT splicing regulation in stem cells and contrasted this with associations of SFs in cancer cells." (PMID 37531400, 2023). "The TERT promoter mutation in the PTC lesion was consistent with the aggressive behavior of the cancer." (PMID 37544981, 2023). "TERT promoter mutations are activating mutations which lead to TERT reactivation and expression from the mutated allele in cancer." (PMID 37993930, 2023). "Somatic mutations in the TERT promoter have been identified with variable frequencies in numerous cancer types." (PMID 38033865, 2023). "In a recent metanalysis, including 19 studies, the mutated TERT promoter was associated with a significantly worse overall survival (hazard ratio 1.43, 95% CI 1.05–1.95), suggesting a major role for telomerase in malignant tumors." (PMID 37296851, 2023). "According to a recent systematic review and meta-analysis including 1830 patients, the overall prevalence of TERT promoter mutations in head and neck cancer was 21% with significant differences according to cancer site." (PMID 38033865, 2023). "In the present study, we successfully introduced DNA methylation specifically to one allele of the TERT promoter in two cancer cell lines with limited effects at the second allele." (PMID 37993930, 2023). "Overall, telomere maintenance is a hallmark of cancer and is often achieved through the reactivation of TERT or ALT pathways, which are associated with the glycolysis." (PMID 38090478, 2023). "The telomerase reverse transcriptase (TERT) gene is essential polymorphic loci linked to most malignant tumors." (PMID 38084250, 2023). "During the last 15 years, extensive studies have been conducted on the role of TERT promoter gene mutation in increasing telomere length and its effect on cancer." (PMID 37383158, 2023).